INS (insulin)
Diseases named in the same sentence as INS in open-access papers (continued):
Sharing a sentence is not in itself a finding about the gene and the disease.
Insulin resistance (continued). "However, compared with low salt rats, fasting insulin and HOMA-IR were significantly increased by 2.3-fold in high salt rats (P ≤ 0.05), indicating insulin resistance." (PMID 20678234, 2010). "Notably, Grb-14 (GRB14) and PTP1B (PTPN1) are known molecular constituents of insulin resistance and development of PTP1B inhibitors for therapeutic modulation of insulin sensitivity is an active field of research." (PMID 20815942, 2010). "In this analysis we utilized a HOMA-IR score derived from a computer program as the method for the measurement of insulin resistance and not insulin resistance measured by clamp or insulin sensitivity by the minimal model." (PMID 21134291, 2010). "The present result showed poor predictive values of preoperatively measured insulin resistance alone and therefore does not support the use of routine preoperative assessment of insulin resistance in cardiac surgery." (PMID 21156037, 2010). "So far, our results suggested that the effect of the serum factor on GLUT4 might be maintained in insulin resistance, as the action of FBS on GLUT4 was largely additive to that of insulin while distinct signaling pathways appeared to be involved." (PMID 21187969, 2010). "HOMA−IR, fasting and 120−minute insulin values, FGIR and total insulin values were significantly different between the subjects of both sexes with and without insulin resistance both in the prepubertal and pubertal groups." (PMID 21274322, 2010). "Moreover, the dynamic during pregnancy of serum T, DHEAS, SHBG, FAI, fasting insulin, GIR and HOMA differed significantly according to the pregnancy outcomes showing an impairment of androgen and free androgen levels and insulin resistance markers." (PMID 20942923, 2010). "In our patients, we did not specifically evaluate all of the components of the metabolic syndrome, but high adiponectinemia did not influence insulin levels, insulin resistance, or changes in lipid profile." (PMID 21234350, 2010). "Moreover, we have recently shown that maintenance of cellular mTOR function by anti-hypertensive drugs improves insulin signaling increasing GLUT 4 expression and prevents micro-vascular rarefaction in spontaneously hypertensive rats with insulin resistance." (PMID 20809949, 2010). "Ghrelin infusion decreased basal as well as insulin stimulated glucose disposal and induced peripheral insulin resistance but did not affect hepatic glucose production." (PMID 20700401, 2010). "They had a lower mean ponderal index and waist circumference, but their mean sum of skinfolds, fat mass index, HbA1c, fasting glucose, fasting insulin, HOMA insulin resistance, C-reactive protein and triglyceride were higher, while HDL-cholesterol levels were lower." (PMID 20421924, 2010). "As hypothesized, participants who were positive for anti-human PDI had significantly higher insulin levels and higher HOMA (Homeostatic Model Assessment of insulin resistance; HOMA = insulin x Glucose/405), compared to anti-human PDI negative subjects." (PMID 20886095, 2010). "Collectively, these studies underscore the important role of JNK in insulin resistance and suggest that inhibitors of JNK-signalling may be used as insulin sensitizing agents." (PMID 20508722, 2010). "Insulin resistance is characterized as the condition that higher level of insulin is required for normal metabolic responses because normal level of insulin fails to achieve these responses in peripheral organs." (PMID 20814441, 2010). "This is consistent with previous observation indicating that T2D is not solely due to insulin resistance but also due to a failure of the insulin producing beta-cells to secrete an adequate amount of insulin." (PMID 20508722, 2010). "It has been reported that blocking NF-κB in macrophages or liver attenuated inflammatory gene expression and insulin resistance on HF diet, c-Jun amino-terminal kinase 1 (JNK1) knockout mice do not become insulin resistant while blocking JNK improves insulin sensitivity." (PMID 20808947, 2010).
Insulin resistance (continued). "As insulin resistance is an integral part of MS and the rate of secondary sulfonylurea failure (SSUF) is also high, the present study was planned to evaluate the effects of insulin sensitizers as add-on therapy in MS with SSUF." (PMID 21350615, 2010). "Each of these parameters (fasting insulin, insulin and blood sugar at 120th minute, FGIR and HOMA−IR values) were compared using the ROC analysis regarding their importance in determination of insulin resistance according to pubertal status and gender." (PMID 21274322, 2010). "For black African-Caribbeans, differences in HbA1c, insulin, insulin resistance, triglyceride, and HDL-cholesterol were not materially affected by adjustment for adiposity." (PMID 20421924, 2010). "However, indices derived from fasting insulin and glucose values, such as HOMA-IR, primarily reflect hepatic insulin resistance, and the accuracy of HOMA-IR in predicting whole-body insulin sensitivity differs among AA and EA." (PMID 20398267, 2010). "While plasma insulin concentrations were not significantly different between diets, insulin resistance (HOMAIR) was significantly improved after the high-CLA beef diet, compared to the control diet (p = 5.1e-06)." (PMID 20929581, 2010). "It has been hypothesized that, by lowering insulin levels, IGF-1 reduces insulin resistance and might thus be of therapeutical importance in physiological states that are associated with insulin resistance, such as type 2 diabetes." (PMID 20414467, 2010). "Whether these differences are of importance during the development of fatty liver, hepatic insulin resistance and impaired glucose tolerance is not known, but it might be speculated that they contribute to a higher risk of developing T2 D in men during situations of insufficient insulin production." (PMID 20863371, 2010). "The clamp data indicate that the absence of OPN leads to improved hepatic insulin sensitivity when mice are fed NC and protection from hepatic and skeletal muscle insulin resistance when mice are fed HFD." (PMID 21103061, 2010). "Nonetheless, these studies did not address the role of insulin action and insulin resistance in myeloid lineage cells under conditions of obesity and obesity-induced inflammation and insulin resistance." (PMID 20463885, 2010). "No signs of functional insulin resistance or perturbed glucohomeostasis were observed as assessed by resting blood glucose and insulin levels, hyperinsulemic-euglycemic clamps, and glucose tolerance tests." (PMID 20851344, 2010). "In the present study, we evaluated the predictive value of simple markers of adiposity for the presence of insulin resistance (measured with the gold-standard euglycemic insulin clamp technique) in a population of adult nondiabetic baboons." (PMID 19389241, 2009). "While whole body insulin resistance was demonstrated by IPGTT and elevated insulin levels at rest and in response to IPGTT, we were interested in validating skeletal muscle insulin resistance and determining if there were muscle-specific differences in insulin resistance in HFD mice." (PMID 19806198, 2009). "LXR SNPs had no impact on fasting plasma glucose or serum insulin, insulin resistance measured as HOMAIR or BMI in either the D.E.S.I.R." (PMID 19292929, 2009). "EGP during the insulin clamp (an index of hepatic insulin resistance) correlated positively with VF/SF ratio but not with BMI, BSA, FM, SF, SSF, DSF, or VF." (PMID 19656356, 2009). "LXR activation has been shown to stimulate insulin secretion in vitro via de novo lipid synthesis, while in vivo LXR agonists are shown to reduce serum glucose levels and to improve glucose tolerance and insulin resistance in obesity models." (PMID 19787047, 2009). "However, the expression of insulin signal proteins (IRS1 and GLUT4) was inhibited in SBRs, which is why prednisolone produces insulin resistance." (PMID 19646276, 2009).
Insulin resistance (continued). "Therefore, it is reasonable to suppose that EA can improve insulin resistance in SBRs by decreasing the plasma FFA levels and recovering insulin signal proteins." (PMID 19646276, 2009). "In contrast, EGP and the product of EGP and SSPI during the insulin clamp (an index hepatic insulin resistance) correlated positively with VF/SF ratio, but not with BMI, FM, VF or SF." (PMID 19656356, 2009). "Adiponectin, which promotes insulin sensitivity by activation of adenosine monophosphate-activated protein kinase (AMPK) and resistin, which has been identified as an adipocyte specific promoter of insulin resistance in mice." (PMID 19087258, 2008). "In insulin resistance, since functionsof internal insulin are largely degraded, it cannot appropriately facilitatethe insulin-glucose metabolism, so regardless of its existence, body cells cannottake in blood glucose enough for energy supply." (PMID 18437199, 2008). "Intake of dietary fibers has been reported to be associated (i) inversely with the probability of having protection against insulin resistance in non-diabetic patients and (ii) with enhanced insulin sensitivity in type 2 diabetes, whatever the type of fiber." (PMID 18847460, 2008). "Without a standard insulin assay, no absolute value can be developed to predict the presence of insulin resistance across laboratories or clinical settings." (PMID 18307789, 2008). "It is well established that insulin resistance is also present in patients without obesity, whereas obese children can be insulin sensitive." (PMID 18700035, 2008). "However, due to the limitations of this model to evaluate insulin action, we examined the role of JNK1 activity in bone marrow-derived elements in development of high fat diet-induced insulin resistance in the C57BL/6 genetic background." (PMID 18773087, 2008). "When insulin resistance reaches extents no longer compensated by the β-cell, insulin secretion declines and hyperglycemia emerges." (PMID 18714373, 2008). "A possible reason is that the HOMAres index is an inaccurate measure of insulin resistance, as it only includes glucose levels at 0 min, whereas insulin does not enter in the algorithm." (PMID 18611252, 2008). "The correlations between serum insulin sensitivity calculated from HOMA-S and serum insulin resistance estimated from HOMA-IR were statistically significant in all subjects, while serum blood glucose, C-peptide, triglycerides, total lipid profile, and IGF-I were not." (PMID 19902049, 2008). "The overall pattern of intergenerational change in glucose-metabolism is similar for both F1 – F3 males and females, however, and among both sexes, insulin resistance (as measured by HOMA), along with fasting insulin and glucose levels, peak in the F2 generation." (PMID 18928547, 2008). "We measured plasma non-esterified fatty acid (NEFA) and insulin levels to follow insulin resistance in our three groups of mice." (PMID 18648539, 2008). "In all the subjects fasting and post-lunch serum IGF-I concentrations were negatively correlated with age, blood glucose, insulin, C-peptide, triglycerides, and total lipid profile with an exception of HDL cholesterol and insulin resistance expressed as HOMA-IR." (PMID 19902049, 2008). "The abnormal signalling produces a form of molecular insulin resistance, although this is not equally severe in all insulin signalling pathways." (PMID 18844978, 2008). "The strain of HSL null mice investigated in the present study exhibits mild insulin resistance that is almost fully compensated by hypersecretion of insulin and no signs of impairment of glucose-stimulated insulin secretion (GSIS)." (PMID 18335062, 2008). "Our findings suggest that in women in the 60–79 y age range, insulin resistance, rather than insulin secretion or chronic hyperglycaemia, is a more important risk factor for coronary heart disease and stroke." (PMID 17760500, 2007).
Insulin resistance (continued). "Second, HOMA is a static measure of insulin resistance, unlike the hyperinsulinemic–euglycemic clamp, which limits its ability to detect abnormalities in insulin secretion or peripheral glucose disposal." (PMID 17589594, 2007). "Although there is no doubt that insulin resistance is the major aetiological factor in the development of MS, direct quantitative measurement of insulin sensitivity is not readily available and thus cannot be used as the diagnostic tool for the syndrome." (PMID 17650158, 2007). "In agreement with previous studies, we found that a 12-week supplement of a flaxseed-derived lignan providing 360 mg/day of SDG did not affect blood lipid profiles, insulin resistance, fasting glucose and insulin concentrations in type 2 diabetic patients." (PMID 17987126, 2007). "Not surprisingly, following discontinuation of insulin sensitization therapy there was an initial partial convergence between the two groups in levels of insulin resistance and sex hormone binding globulin (SHBG) from 36 months to 48 months." (PMID 17608755, 2007). "Regarding these markers for insulin resistance, those patients with either insulin resistance or AGT comprise the majority of PCOSaffected patients (AGT + fasting insulin ≥17: 83%, AGT + glucose/insulin ratio ≥6.5: 85.1%, AGT + HOMAIR ≥2: 87.2%, and AGT + HOMAIR ≥3.8: 72.3%)." (PMID 16603055, 2006). "This experiment indicates that, in the E2-treated animals, there was mild insulin resistance, because there are 1.7-fold higher circulating insulin levels but a decrease of blood glucose, although it is not significant." (PMID 16393666, 2006). "This latter finding was still significant after adjusting for insulin resistance, suggesting that it is not secondary to the possible increase in insulin sensitivity that we observed." (PMID 17181866, 2006). "Our study raises the possibility that an initial exacerbation of glucose tolerance, apparently due to insulin resistance, might, after prolonged treatment with a high dose of CLA, be followed by improved insulin sensitivity and glucose tolerance." (PMID 15642120, 2005). "Because insulin signaling occurs partially through PI-3-kinase, increased expression of Sh3kbp1 by DIO mice may contribute to hepatic insulin resistance via inhibition of PI-3-kinase." (PMID 15985155, 2005). "Therefore if PTP4a2 also negatively regulates insulin signaling, its significant downregulation (p < 0.01) following 10 weeks of high-fat feeding may be a physiological adaptation that protects hepatocytes against insulin resistance, which is normalized by fasting/ weight reduction." (PMID 15985155, 2005). "Since PPARγ agonists increase insulin sensitivity but promote adipogenesis, decreased activity of PPARγ in adipose tissue could explain why CLA reduces obesity but increases insulin resistance." (PMID 15642120, 2005). "Note that insulin sensitivity is important for weight gain and accumulation of VAT, and investigators have proposed that insulin resistance may actually, to a certain extent, be beneficial by protecting cells with already impaired fatty acid oxidation." (PMID 15530168, 2004). "Although both TAG and DAG accumulations in skeletal muscle were reported to be correlated with insulin resistance, DAG (a precursor of TAG synthesis) is proposed to directly impair insulin sensitivity by inactivating insulin receptor activity through activation of the protein kinase C." (PMID 15507149, 2004). "Second, although HFD is often associated with insulin resistance, we did not directly measure fasting glucose, insulin, or insulin sensitivity; therefore, the metabolic phenotype of this model is interpreted primarily as obesity/dyslipidemia rather than insulin resistance." (PMID 41602450, 2026). "Likewise, insulin, HOMA-IR, and QUICKI showed no meaningful association, and multicollinearity was evident among insulin resistance markers (VIF > 20)." (PMID 41596434, 2026).
Insulin resistance (continued). "However, when we calculated whole-body insulin resistance using the insulin sensitivity index developed by Matsuda (ISIMatsuda), we found reduced insulin sensitivity in pwCF GI, but not in pwCF NGT, compared with non-CF NGT." (PMID 41489009, 2026). "Importantly, GSK‐3 is a stress kinase that can also impair insulin signaling and glucose metabolism, and inhibition of GSK‐3 is well known to improve whole‐body insulin resistance and glucose metabolism and, as such, is being investigated as a potential AD therapy." (PMID 41559866, 2026). "Importantly, the TAG:FBG index (Tyg index) has been strongly correlated with the hyperinsulinemic-euglycemic clamp, the gold standard for assessing insulin sensitivity and has been proven to be better than the HOMA-IR for evaluation of insulin resistance/sensitivity." (PMID 41493485, 2026). "Positive correlations were also observed with highly sensitive C-reactive protein (hs-CRP), insulin, glucose, triglycerides, and Homeostasis Model Assessment of Insulin Resistance (HOMA-IR), and a negative correlation was found with high-density lipoprotein (HDL) cholesterol." (PMID 41598707, 2026). "Second, we did not use in vitro models of insulin resistance, which could provide additional insights concerning the effect of these agents on insulin action." (PMID 40793247, 2025). "Given the potential role of iatrogenic peripheral hyperinsulinemia in worsening insulin resistance and endothelial dysfunction, we hypothesized that reducing this hyperinsulinemia via an RCD would improve insulin sensitivity and endothelial function in individuals with type 1 diabetes." (PMID 40045281, 2025). "However, TRPV1−/− mice on HFD ± CAP exhibited only a modest decline in blood glucose levels after insulin injection, indicating persistent insulin resistance and a lack of CAP efficacy in the absence of TRPV1." (PMID 40864772, 2025). "Since fasting insulin (among other things) is not tested routinely despite the prevalence of insulin resistance, a significant proportion of people may go undiagnosed, and the condition may progress gradually for years." (PMID 40901288, 2025). "Due to lack of data (insulin level) of the remaining three patients, their insulin resistance status was unknown." (PMID 41233800, 2025). "Thus, T2D iHeps showed evidence of selective insulin resistance in gene expression, such that insulin did not suppress gluconeogenesis normally but had an exaggerated response on de novo lipogenesis." (PMID 40231468, 2025). "Thus, larger cohorts are needed that consist of non-insulin-resistant, prediabetes (impaired fasting blood glucose and/or impaired insulin tolerance), and T2D patients to support the decline in TAS1R3 with the progression of insulin resistance." (PMID 41515983, 2025). "The core features of the DASH diet show improvements in insulin sensitivity and β-cell function, which may be of particular value for metabolic control in patients with LADA because of both autoimmune destruction and insulin resistance features." (PMID 41229546, 2025). "Notably, ZFYVE28 is found to mediate insulin resistance, with higher expression levels in obese, non-diabetic patients (insulin resistant individuals)." (PMID 40656995, 2025). "There are several non-insulin-based, newly raised, and well-established indexes to represent IR in our study, including the Triglyceride-Glucose (TyG) index, the Atherogenic Index of Plasma (AIP) index, and the Metabolic Score for Insulin Resistance (METS-IR) index." (PMID 41040505, 2025). "However, it has also been shown that lack of AhR improved insulin sensitivity and glucose tolerance by increasing energy expenditure and ameliorating high-fat diet-induced insulin resistance in mice." (PMID 39944639, 2025).